INTS3 (integrator complex subunit 3)
Description:
Component of the integrator complex, a multiprotein complex that terminates RNA polymerase II (Pol II) transcription in the promoter-proximal region of genes. The integrator complex provides a quality checkpoint during transcription elongation by driving premature transcription termination of transcripts that are unfavorably configured for transcriptional elongation: the complex terminates transcription by (1) catalyzing dephosphorylation of the C-terminal domain (CTD) of Pol II subunit POLR2A/RPB1 and SUPT5H/SPT5, (2) degrading the exiting nascent RNA transcript via endonuclease activity and (3) promoting the release of Pol II from bound DNA. The integrator complex is also involved in terminating the synthesis of non-coding Pol II transcripts, such as enhancer RNAs (eRNAs), small nuclear RNAs (snRNAs), telomerase RNAs and long non-coding RNAs (lncRNAs). Within the integrator complex, INTS3 is involved in the post-termination step: INTS3 binds INTS7 in the open conformation of integrator complex and prevents the rebinding of Pol II to the integrator after termination cycle. Mediates recruitment of cytoplasmic dynein to the nuclear envelope, probably as component of the integrator complex. Component of the SOSS complex, a multiprotein complex that functions downstream of the MRN complex to promote DNA repair and G2/M checkpoint. The SOSS complex associates with single-stranded DNA at DNA lesions and influences diverse endpoints in the cellular DNA damage response including cell-cycle checkpoint activation, recombinational repair and maintenance of genomic stability. The SOSS complex is required for efficient homologous recombination-dependent repair of double-strand breaks (DSBs) and ATM-dependent signaling pathways. In the SOSS complex, it is required for the assembly of the complex and for stabilization of the complex at DNA damage sites.
Synonyms: Int3; SOSS-A; C1orf193; C1orf60; FLJ21919; SOSSA
Tractability: PROTAC: ubiquitination databases record sites on it; its protein half-life has been measured.
Gene: Protein-coding gene on chromosome 1 (153,728,050 to 153,774,808, forward strand). Ensembl gene ENSG00000143624.
Subcellular location: Nucleus; Cytoplasm
Subcellular location (Human Protein Atlas): Nucleoli; Nucleoplasm
Pathways (Reactome):
Gene expression (Transcription): RNA polymerase II transcribes snRNA genes
Gene Ontology:
Molecular function: protein binding
Biological process: DNA damage response; DNA repair; double-strand break repair via homologous recombination; mitotic G2/M transition checkpoint; regulation of transcription elongation by RNA polymerase II; response to ionizing radiation; RNA polymerase II transcription initiation surveillance; snRNA processing
Cellular component: cytoplasm; INTAC complex; integrator complex; nucleoplasm; nucleus; site of double-strand break; SOSS complex
Genetic constraint (gnomAD): Loss-of-function variants: 31 observed, 122.26 expected, observed/expected ratio (o/e) 0.25, 90% interval 0.19 to 0.34. The upper end of that interval is the gene's LOEUF score, 0.34, which puts it in group 1 of 6, group 1 being the genes least tolerant of losing a copy. Missense variants: 676 observed, 1,239.4 expected, observed/expected ratio (o/e) 0.55, 90% interval 0.51 to 0.58. Synonymous variants: 444 observed, 480.73 expected, observed/expected ratio (o/e) 0.92, 90% interval 0.85 to 1.
Homologues: Orthologues: chimpanzee INTS3 (100% identical), macaque INTS3 (100% identical), pig INTS3 (99% identical), rabbit INTS3 (99% identical), dog INTS3 (99% identical), mouse Ints3 (99% identical), rat Ints3 (98% identical), guinea pig INTS3 (96% identical), zebrafish ints3 (83% identical), tropical clawed frog INTS3 (77% identical), Drosophila melanogaster IntS3 (40% identical), Caenorhabditis elegans ints-3 (24% identical).
Diseases named in the same sentence as INTS3 in open-access papers:
INTS3 is named in the same sentence as 12 diseases in open-access papers, as found by Europe PMC text mining. Sharing a sentence is not in itself a finding about the gene and the disease. The quoted sentences say what the papers report.
leukemia (2 papers, 2019 to 2024). A malignant (clonal) hematologic disorder, involving hematopoietic stem cells and characterized by the presence of primitive or atypical myeloid or lymphoid cells in the bone marrow and the blood. "The abnormal splicing of INTS3 caused by the mutant SRSF2 binding to cis elements in INTS3 mRNA, along with the increased DNA methylation of INTS3 caused by the mutant IDH2, plays a role in the development of leukemia." (PMID 39034387, 2024). "Each validated gene in this category, i.e., CD3G, DFFA, GIGYF1, GIGYF2, and INTS3 were shown to play a role in neoplastic processes, including leukemia." (PMID 31709175, 2019).
colon cancer (1 paper, 2020). "Based on our network, CLK2, INTS3, and XAB2 may function as oncoproteins because that the high expression of these SFs showed poor survival of colon cancer." (PMID 32962686, 2020).
diffuse large B-cell lymphoma (1 paper, 2017). "A global low mutation rate (from 0 to 9.09%) was found, with INTS3 and INTS7 being frequently mutated in lymphoid neoplasm diffuse large B-cell lymphoma (DLBC) (8.16%) and in pancreas adenocarcinoma (PAAD) (9.1%), respectively." (PMID 28468258, 2017).
hepatocellular carcinoma (1 paper, 2017). A malignant tumor that arises from hepatocytes. "Similarly, INTS3 was found to be significantly overexpressed in cell lines and tumor tissues from hepatocellular carcinoma (HCC) patients compared with their non-cancerous counterparts." (PMID 28468258, 2017).
cancer (3 papers, 2015 to 2025). A tumor composed of atypical neoplastic, often pleomorphic cells that invade other tissues. "Consistently, we identified that in U2OS cancer cells, hSSB1 protein associates with RNA polymerase II via INTS3." (PMID 36811381, 2023). "Finally, INTS3/SAGE1 regulates transcription by directly interacting with RNA polymerase II, a direct target in the transcription of genes involved in cancer." (PMID 40278293, 2025).
infection (2 papers, 2020 to 2024). The state of being infected such as from the introduction of a foreign agent such as serum, vaccine, antigenic substance or organism. "At 6 hours post infection (hpi), we observed Ints3 and Ints4 colocalization with EdC-labeled HSV-1 DNA, supporting previous results that the Integrator complex copurifies with HSV-1 genomes." (PMID 38817634, 2024). "Upon infection, DC displayed the down-regulation of a gene related to the DNA repair and mitotic cell cycle, INTS3, and the up-regulation of RSBN1, a gene involved in chromatin organization." (PMID 33365028, 2020). "In addition, these data suggest that Ints3 does not play a major role in the DNA damage response during infection to either promote or inhibit infection under the experimental conditions tested in this study." (PMID 38817634, 2024). "This suggests that Ints3 may serve a redundant or nonessential function with respect to infection." (PMID 38817634, 2024).
tumor (2 papers, 2023 to 2024). "We then examined the expression of proteins associated with INTS1, INTS3, INTS4, INTS7, and INTS8 in HCC through the Clinical Proteomic Tumor Analysis Consortium (CPTAC) and Human Protein Atlas (HPA) databases." (PMID 38926181, 2024). "While INTS3 showed both characteristics and revealed tumor suppression in hematology malignancy but turned to an oncogene in the solid organ malignancy." (PMID 37537630, 2023). "However, some studies have recently revealed its involvement in tumor development, including INTS3, INTS6, INST7, and INSTS8." (PMID 37537630, 2023). "Therefore, we analyzed the differential expression of INTS1, INTS3, INTS4, INTS7, and INTS8 in normal, further tumor, and metastatic HCC tissues using the TNM plotter." (PMID 38926181, 2024).
INTS3 also shares sentences with these, for which no sentence is quoted: acute myeloid leukemia (1 paper); lymphoid neoplasm (1); Miller-Dieker syndrome (1); ovarian carcinoma (1); pancreas adenocarcinoma (1).